ACAD8 (acyl-CoA dehydrogenase family member 8)
Description:
Isobutyryl-CoA dehydrogenase which catalyzes the conversion of 2-methylpropanoyl-CoA to (2E)-2-methylpropenoyl-CoA in the valine catabolic pathway. To a lesser extent, also able to catalyze the oxidation of (2S)-2-methylbutanoyl-CoA.
Synonyms: IBDH; ARC42; ACAD-8
Tractability: Small molecule: a structure with a bound ligand is known; it has a high-quality binding pocket. PROTAC: ubiquitination databases record sites on it; its protein half-life has been measured.
Gene: Protein-coding gene on chromosome 11 (134,253,514 to 134,265,855, forward strand). Ensembl gene ENSG00000151498.
Subcellular location: Mitochondrion
Pathways (Reactome):
Metabolism: Branched-chain amino acid catabolism
Metabolism of proteins: Mitochondrial protein degradation
Gene Ontology:
Molecular function: protein binding; short-chain 2-methyl fatty acyl-CoA dehydrogenase activity; acyl-CoA dehydrogenase activity; flavin adenine dinucleotide binding; oxidoreductase activity, acting on the CH-CH group of donors; short-chain fatty acyl-CoA dehydrogenase activity
Biological process: lipid metabolic process; L-valine catabolic process
Cellular component: mitochondrion; mitochondrial matrix
Genetic constraint (gnomAD): Loss-of-function variants: 45 observed, 51.97 expected, observed/expected ratio (o/e) 0.87, 90% interval 0.68 to 1.11. The upper end of that interval is the gene's LOEUF score, 1.11, which puts it in group 4 of 6, group 1 being the genes least tolerant of losing a copy. Missense variants: 494 observed, 551.14 expected, observed/expected ratio (o/e) 0.9, 90% interval 0.83 to 0.97. Synonymous variants: 198 observed, 207.62 expected, observed/expected ratio (o/e) 0.95, 90% interval 0.85 to 1.07.
Gene-disease validity (ClinGen):
ClinGen rates the evidence that ACAD8 causes each of these diseases.
isobutyryl-CoA dehydrogenase deficiency (autosomal recessive): Definitive. An inborn error of valine metabolism.
Homologues: Orthologues: chimpanzee ACAD8 (99% identical), macaque ACAD8 (92% identical), mouse Acad8 (89% identical), rat Acad8 (89% identical), guinea pig ACAD8 (87% identical), pig ACAD8 (87% identical), dog ACAD8 (87% identical), tropical clawed frog acad8 (77% identical), zebrafish acad8 (77% identical), Caenorhabditis elegans acdh-9 (56% identical). Paralogues in human: ACADS (35% identical), ACADSB (33% identical), ACAD9 (32% identical), ACADM (32% identical), ACADVL (30% identical), IVD (30% identical), ACADL (29% identical), GCDH (26% identical), ACAD11 (24% identical), ACAD10 (23% identical), ACOX3 (23% identical), ACOXL (19% identical), and 2 more.
Diseases named in the same sentence as ACAD8 in open-access papers:
ACAD8 is named in the same sentence as 19 diseases in open-access papers, as found by Europe PMC text mining. Sharing a sentence is not in itself a finding about the gene and the disease. The quoted sentences say what the papers report.
(IBD) deficiency (2 papers, 2021 to 2025). "Isobutyryl-CoA dehydrogenase deficiency (IBDD) is a rare autosomal recessive metabolic disorder resulting from variants in ACAD8, and is poorly understood, as only dozens of cases have been reported previously." (PMID 34544473, 2021). "Isobutyryl-CoA dehydrogenase (IBD) deficiency (IBDD, OMIM#611283) is a rare autosomal recessive metabolic disorder involving defects in valine metabolism, which is caused by biallelic variants in ACAD8 (acyl-CoA dehydrogenase family member 8; OMIM*604773) on chromosome 11q25." (PMID 34544473, 2021).
cardiac hypertrophy (2 papers, 2023 to 2026). "Here, we show that the levels of ACAD8 are reduced in humans and male mice with cardiac hypertrophy." (PMID 42115600, 2026). "Conversely, ACAD8 overexpression in cardiomyocytes suppresses isobutyryl-CoA accumulation and histone isobutyrylation, thereby attenuating cardiac hypertrophy and dysfunction." (PMID 42115600, 2026). "Cardiomyocyte-specific Acad8 knockout in male mice exacerbates cardiac hypertrophy and cardiac dysfunction underwent pressure overload." (PMID 42115600, 2026). "miR-23b-5p, which we predicted to target Acad8, is also known to target Hmgb2 and thereby play a role in cardiac hypertrophy." (PMID 37167320, 2023).
fatty liver (2 papers, 2021 to 2024). "Similar to our findings, Zengpeng and colleagues demonstrated that dietary genistein supplementation resulted in the upregulation of gene transcription associated with fatty acid beta-oxidation, including PPARα, PPARδ, ACOT8, ACAD8, and ACADs in the liver of laying hens induced fatty liver." (PMID 38540097, 2024). "However, Acad8 mutant mice showed significantly elevated transaminase levels and presented progressive hepatic steatosis." (PMID 34544473, 2021).
Obesity (2 papers, 2020 to 2025). Accumulation of substantial excess body fat. "ACAA2 and ACAD8 are proteins mainly catalyze dehydrogenation steps of β-oxidation processes in mitochondrial fatty acids catabolism, HIBCH involving in energy metabolism by regulating fat hydrolysis in obesity mice." (PMID 32053710, 2020).
atopic dermatitis (1 paper, 2024). "In atopic dermatitis, genes mainly related to lipid metabolism (e.g. ACAD8, FADS6, or EBP) as well as disease-specific genes, i.e., Th2 inflammation-related lipid-regulating HSD3B1 were differentially expressed." (PMID 38433843, 2024).
cardiomyopathy (1 paper, 2026). A disease of the heart muscle or myocardium proper. "Genetic deficiency in the valine catabolic enzyme ACAD8 is clinically associated with isobutyryl-CoA deregulation and cardiomyopathy in humans, but its roles in cardiac disease remain undefined." (PMID 42115600, 2026).
colorectal cancer (1 paper, 2025). A primary or metastatic malignant neoplasm that affects the colon or rectum. "KEGG analysis revealed that ACAD8 is associated with several signaling pathways, including the PI3K-Akt signaling pathway, Cell adhesion molecules, Colorectal cancer and Hippo signaling pathway." (PMID 40248707, 2025).
developmental delay (1 paper, 2021). "Notably, one case harbored both ACAD8 compound heterozygous variants and a KMT2A de novo variant (c.2739del, p.E914Rfs*35), with IBDD and Wiedemann–Steiner syndrome together, had exact severe global developmental delay." (PMID 34544473, 2021).
steatosis (1 paper, 2023). Increased lipid within the cytoplasm of cells. "ACAD8 is a gene encoding isobutyryl-CoA dehydrogenase, the dysregulation of which leads to hepatic steatosis via mitochondriopathy." (PMID 37445858, 2023).
tumor (4 papers, 2019 to 2025). "As a novel tumor suppressor, low expression of CRGs-ACAD8 is associated with the metastasis of CRC." (PMID 40248707, 2025). "In the context of cancer research, ACAD8 has been associated with a favorable prognosis in lung adenocarcinoma (LUAD), where it is considered a tumor-associated fibroblast-related gene associated with good survival outcomes." (PMID 40248707, 2025). "In conclusion, in CRC, as CRGs, ACAD8 inhibits tumor metastasis by inducing cuproptosis and suppressing cell proliferation, stemness, and migration ability." (PMID 40248707, 2025). "Future research will further explore the relationship between ACAD8 and immune cell types and distribution, as well as its interactions with tumor cells, to enable more personalized and precise immunotherapy strategies." (PMID 40248707, 2025). "Using TCGA, we analyzed ACAD8 expression differences in mCRC and validated the findings with GEO and tumor samples from CRC patients at Fujian Provincial Hospital." (PMID 40248707, 2025). "Limited information is available on the role of ACAD8 in the TME, which is regarded as a tumor-associated fibroblast-related gene associated with good survival outcomes." (PMID 39735553, 2024). "Our analysis reveals that ACAD8 plays an important role in immune infiltration within CRC, suggesting that ACAD8 may suppress tumor metastasis by activating immune cell infiltration." (PMID 40248707, 2025). "Future studies could explore the potential therapeutic applications of ACAD8 in various cancers, particularly in the context of amino acid metabolism and its impact on tumor progression and immune response." (PMID 40248707, 2025). "Besides, ACAD8, the acyl‐CoA dehydrogenase family member 8, was detected to be upregulated in tumor tissues in this study." (PMID 31495056, 2019). "This study confirms that ACAD8, as a CRG, is a novel tumor suppressor in CRC, inhibiting metastasis by inducing cuproptosis." (PMID 40248707, 2025). "Tumor-bearing nude mice treated with neoantigen (ACAD8-T105I, BCAR1-G23V and PLCG1-M425L)-induced NRTs exhibited significantly delayed tumor growth, whereas the irrelevant peptide-induced NRTs did not restrict tumor growth." (PMID 33928024, 2021).
cancer (2 papers, 2015 to 2025). A tumor composed of atypical neoplastic, often pleomorphic cells that invade other tissues. "Paired sample analysis across pan-cancer also indicated differential expression of ACAD8 in 14 cancer types." (PMID 40248707, 2025). "We further analyzed the correlation between ACAD8 expression and immune cell infiltration across pan-cancer datasets." (PMID 40248707, 2025). "Additionally, the role of ACAD8 in other cancers and its potential therapeutic applications also require in-depth investigation." (PMID 40248707, 2025). "After confirming ACAD8 expression in CRC, we examined whether there were also expression differences in pan-cancer." (PMID 40248707, 2025).
autosomal recessively inherited disease (1 paper, 2019). "This condition is an autosomal recessively inherited disease and caused by mutations in the ACAD8 gene." (PMID 31737040, 2019).
ACAD8 also shares sentences with these, for which no sentence is quoted: metabolic disease (2 papers); cardiac disease (1); glutaric acidemia type II (1); hyperprolinemia (1); infection (1); Niemann-Pick disease, type C2 (1); prostate tumors (1).